IDO1 (indoleamine 2,3-dioxygenase 1)
Diseases named in the same sentence as IDO1 in open-access papers (continued):
Sharing a sentence is not in itself a finding about the gene and the disease.
cancer (continued). "The basis for this observation and later observations in various types of cancer patients was not clear until IDO1 was discovered in the 1960s." (PMID 30254983, 2018). "Finally, we found that IDO1 and the cytotoxic molecules including PRF1 and GZMA had a positive correlation with the PD-1 in most cancer types." (PMID 30607140, 2018). "However, IFN-γ also mediates feedback inhibition and up-regulates PD-L1, PD-L2 and other checkpoint molecules such as IDO1, TIGIT, and LAG3, thus allowing cancer cells to survive." (PMID 30477280, 2018). "We determined the expression of IDO1, IDO2, and TDO in cancer cells treated with IFN-γ." (PMID 29685162, 2018). "The combination of IDO inhibitors to the immunotherapy clearly increased the anti-cancer effects by reducing the negative impact of IDO1 expression on the protective immunity induced by the vaccine." (PMID 30186285, 2018). "Additionally, however, we noted a specific set of genes encoding chemokines and cytokines, namely CCL4, CCL8, CXCL10, CXCL11, IFI44L, IDO1, and IFNG that were upregulated in 9p CNG cancers." (PMID 29212506, 2017). "Increased IDO1 expression was also found in hypermutated colorectal cancers, but not in non-hypermutated cancers, suggesting its role in blunting immune responses elicited against neoepitopes in these tumors." (PMID 29283429, 2017). "The role of IDO1 and IDO2 in cytotoxic T-cell responses directed against self has been reviewed recently with a perspective on regulating this response in the setting of cancer therapy." (PMID 25477879, 2014). "This review provides a comprehensive analysis of IDO1-targeted therapeutic development, examining both the clinical experience with conventional inhibitors and the emerging potential of PROTAC-based degraders, while discussing their implications for the future of cancer immunotherapy." (PMID 40894232, 2025). "Furthermore, a variety of cancer cells and antigen-presenting cells APCs demonstrate that IL-6, IFN-γ, TGF-β, CTLA-4 and programmed cell death protein 1 (PD-1) can all induce high levels of IDO1." (PMID 41035912, 2025). "In contrast, IDO1 (indoleamine 2,3-dioxygenase 1), which is involved in tryptophan metabolism, and ALOX15 (arachidonate 15-lipoxygenase), which regulates the metabolism of polyunsaturated fatty acids, were highly overexpressed in iPSCs compared to MSCs and cancer cell lines." (PMID 39621192, 2025). "Regardless of their mechanism of inhibition, EPA, LIN, and NAV could stabilize and prolong the half-life of the non-enzymatic IDO1 protein conformation in various cancer types, including solid and hematological tumor cell lines." (PMID 41262240, 2025). "Considering that IDO2 and TDO are poorly known in the field of cancer, future studies should also consider whether blocking TDO and/or IDO2 could provide general efficacy and reduce the inherent or acquired resistance to IDO1 blockade." (PMID 39371092, 2024). "However, the development of the catalytic inhibitors of IDO1 has not yet provided a licensed anti-cancer drug and has experienced a significant setback after the failure of epacadostat in phase III trial." (PMID 38333210, 2024). "Dual targeting of IDO1 and TDO2 may be impactful in other cancer types." (PMID 38451784, 2024). "In cancer, the corresponding signal transduction after PRR stimulation amplifies the effect of the immunosuppressive response of MDSCs by producing a variety of proteins, including arginase-1, iNOS, IDO-1, prostaglandin E2, PD-L1, CD40, TNF-α, IL-1β, IL-6, cyclooxygenase-2, and others." (PMID 39035356, 2024).
cancer (continued). "Suppose PDL1 (like LAG3) is not only a CPI but also a stemness marker (unlike other CPI), could that explain why anti-PD1/L1 (and anti-LAG3) is a better anti-cancer treatment compared with those other CPI (e.g., anti-CTLA4, anti-IDO1, anti-TIGIT), which are bona fide immunotherapy?" (PMID 38539487, 2024). "When we believe that immunotherapy could be a panacea in cancer care, we combine anti-PD1/L1 with another CPI (such as anti-CTLA-4, anti-IDO1, anti-TIGIT) and with agents that target immune factors (e.g., IL-2) and effectors (e.g., dendritic cells, T cells, macrophages, NK cells), etc." (PMID 38539487, 2024). "This raises the question of whether IDO1 might have a broader role supporting neovascularization in inflammatory pathologies that do not involve cancer." (PMID 37182174, 2023). "This is exemplified by our own findings that tumoral KYNU, but not IDO1, is selectively and frequently upregulated in NRF2 activated tumors and that elevated tumoral KYNU is associated with high immune cell infiltration across several cancer types." (PMID 37876966, 2023). "Compared with previous studies that investigated the value of TMEscore in other cancers, our study constructed a four-gene TME signature using TMEscore-related genes (CXCL10, LZTS2, IDO1, and MAB21L2), making it easy for clinicians to assess patients who might belong to the TME-H or TME-L signature." (PMID 37596528, 2023). "In contrast, T-cells expressing PD-L1, B7-H3, B7-H4, IDO-1, and OX40, which were less abundant, were located close to the malignant cells, suggesting that the distance from malignant cells and pattern of distribution, rather than the density of these cells, play a critical role in cancer." (PMID 37185575, 2023). "Moreover, a previous study showed that increased KTR, a clinical marker of IDO1 activity, is a negative prognostic factor for cancer-specific and progression-free survival." (PMID 36902242, 2023). "Nevertheless, experimental evidence supporting the rationale for using IDO1 as a drug target for cancer therapy would be welcome irrespective of whether it is the immune-cell IDO1 or the cancer-cell IDO1 that elicits the therapeutic effect." (PMID 35997090, 2022). "Mmp7+ Paneth-like cancer cells were present in Tyk2Δ/Δ, but they did not express Ido1." (PMID 36185806, 2022). "The mechanism for how cancer cells overcome IDO1-mediated tryptophan deprivation is not elucidated and is a current interesting scientific speculation." (PMID 36613455, 2022). "Moreover, inhibitor 3 was found to have the most effective inhibition of IDO1 in MCF-7 cancer cells without toxic effects." (PMID 35563059, 2022). "Thus, developing dual inhibitors of IDO1 and TDO2 might be an effective method for cancer immunotherapy." (PMID 35571116, 2022). "This may be in line with other reports showing that TDO/KP could be involved in cancer biology, particularly when IDO1 does not account for the constitutive Trp catabolism." (PMID 33806305, 2021). "However, the enzymatic activity of the IDO1 enzyme measured indirectly as the level of l-Kyn production showed a difference between the cancer and noncancerous cells." (PMID 33922995, 2021). "Indolamine, 2,3-dioxygenase-1 (IDO1) and IDO2 are two related, initial rate-limiting enzymes (along with the unrelated enzyme TDO) in the KP and have aroused great interest with regard to inducing cancer immunosuppression, tumor development, and metastasis and neovascularization." (PMID 34681715, 2021). "IDO1 also induces cancer progression in a non-immune manner by regulating angiogenesis." (PMID 33747948, 2021). "Compared with other subtypes, Luminal A cancer had the lowest expression of PD-L1 and IDO1, suggesting that IDO1 may play important role in TNBC but not Luminal A cancers." (PMID 34381711, 2021). "In our study, using IDO1 inhibitor alone could not get an expected result, but resulted in upregulation of IDO1 and PD-L1 in several types of cancer cells." (PMID 34175886, 2021).
cancer (continued). "Especially cancer patients with no response to immune checkpoint inhibitors might benefit from an additional IDO1 inhibition." (PMID 32153576, 2020). "In addition to the T cell suppression activity, IDO1 has been reported to support cancer growth in a non-immunomodulation way." (PMID 32545442, 2020). "Although the non-immune functions of IDO1 have been reported in some cancer types, the involvement of IDO1 in the characteristics of cervical CSCs remains unclear." (PMID 32545442, 2020). "Due to the fact that possible inhibition of IDO1 by specific inhibitors would decrease NAD+ in human cancer cells and that NAD+ is crucial for PARP1 activity, we hypothesize that double-hit therapy of IDO1 and PARP1 inhibitors would be a promising combination treatment." (PMID 32380691, 2020). "However, the role of extracellular secretion of IDO1 in cancer progression has not yet been described." (PMID 33552086, 2020). "Therefore, the discovery of dual IDO1 and HDAC inhibitors may provide a novel strategy for cancer treatment by taking advantages of both immunotherapeutic and epigenetic drugs." (PMID 33007982, 2020). "The aim of this study was to use CCLE (Cancer Cell Line Encyclopedia) transcriptomic data of GC cell lines for WGCNA (Weighted Gene Co-expression Network Analysis) analysis, and explore the potential functions and mechanisms of IDO1 in GC progression in vitro and in vivo." (PMID 31315643, 2019). "In contrast, neither the IDO1 inhibitor nor the BET inhibitors greatly affected the proliferation of the cancer cells exposed to the same treatments, indicating that the reduction of the l-kynurenine production caused by these inhibitors is independent of their proliferative inhibition." (PMID 31324754, 2019). "To date, no IDO1 inhibitors are approved by the FDA to treat cancer." (PMID 29685162, 2018). "Overexpression of other cancer-immunity cycle markers were also observed including myeloid suppression markers (e.g. CCL2, CCR2 and CSF1R; 10-22%), metabolic immune escape markers (e.g. ADORA2A and IDO1; 9-16%) and T-cell primed markers (e.g. CD40, GITR, ICOS and OX40; 4-26%)." (PMID 30400835, 2018). "Moreover, CD8+ T cells infiltrating IDO1-transduced lungs exhibited impaired effector functions due to selective IDO-mediated inhibition of mitochondrial electron transfer, a finding reminiscent of functional impairment of tumor-infiltrating T cells in cancer." (PMID 29163470, 2017). "AhR-mediated non-genomic modulation of IDO1 might provide druggable targets in cancer therapy, in alternative to or in combination with the already available enzyme inhibitors." (PMID 25360135, 2014). "The IDO1-driven production of KYN promotes the development, stabilization and activation of Treg cells, while suppressing effector T cells, all of which may contribute to immune system impairment in cancer-bearing individuals." (PMID 23232072, 2012). "However, a review article on the application of IDO1 inhibitors in cancer immunotherapy indicates that studies on IDO1 inhibitors have not produced the expected benefits for cancer patients, regardless of whether they have gastrointestinal tumors." (PMID 40909948, 2025). "Furthermore, it is intriguing that IFN-γ promoted IDO1 expression but not cancer cell apoptosis." (PMID 38540186, 2024). "Furthermore, we show that IL4I1, IDO1, or AHR high expression correlates with poorer survival of LGG patients, and that high IL4I1 expression also correlates with poorer outcome in GBM patients, confirming the clinical relevance of this pathway in these cancers." (PMID 38937431, 2024). "On one hand, IFN-γ is the most prominent inducer of the IDO1 gene; on the other hand, although several studies demonstrate that IFN-γ could induce the expression of IDO2 in human mesenchymal stem cells and some cancer cells, in human dendritic cells, the cytokine is ineffective." (PMID 39594642, 2024). "In addition, evidence suggests that IDO1, TDO and IDO2 may all play a role in malignant tumours." (PMID 37644823, 2023).
cancer (continued). "Furthermore, we show that IL4I1, IDO1, or AHR high expression correlate with poorer survival of LGG patients, and that high IL4I1 expression also correlates with poorer outcome in GBM patients, confirming the clinical relevance of this pathway in these cancers." (PMID 37986881, 2023). "Thus, the non-immune role of IDO1 in the cancer microenvironment should be considered." (PMID 36233312, 2022). "However, the immune regulator function of IDO1 in different types of cancer could not be completely consistent." (PMID 36212460, 2022). "However, the expression of other T-cell inhibitory receptors, such as Tim-3 (Havcr2) or Lag-3, and the cancer immune evasion-related factor Pak4 remained unchanged in MUP-uPA mice, regardless of the type of diet fed in parallel to the unchanged expression of indoleamine 2,3-dioxygenase (Ido1)." (PMID 34439245, 2021). "Administration of IDO1 inhibitors may be beneficial to certain but not all cancers." (PMID 30150994, 2018). "Our results demonstrated the significantly negative correlations of m7Gscore with the expression of IDO1, PDCD1, and LAG3, which have been considered as important targets for cancer immunotherapy." (PMID 36246663, 2022). "The role of Ido1 in CRC and in cancer in general is not well defined, but several studies have reported an oncogenic activity." (PMID 36185806, 2022). "CD8A expression was correlated with all three genes in 22 cancer types, and with IDO-1 and IDO-2 (but not TDO-2) in nine more cancer types, so CD8+ T-cell infiltration is likely a widespread predictor of IDO pathway over-expression." (PMID 34367262, 2021). "Nevertheless, an important contribution of both IDO1 and IDO2 in cancer development, not mentioned before, is their involvement in NAD+ production." (PMID 34071442, 2021). "Regarding gene expression, cancer immune evasion-related genes were found up-regulated in the negative BL samples, such as CD274 (alias PD-L1), IDO1, LAG-3, CTLA4, and CD80 and CD86 genes, required for the activation of the inhibitory activity of CTLA4." (PMID 34680332, 2021). "Amongst more than 200 genes induced by IFN-γ, many of those genes are the molecules involved in cancer cell immune evasion, such as PD-L1, PD-L2, CTLA-4, CIITA, non-classical MHC class Ib antigens, IDO1, CXCL12 etc.." (PMID 29283429, 2017). "Recently, studies have shown clinical benefit of IDO1 inhibitors in phase I and II clinical trials in melanoma, but not in phase III, delineating the need to identify cancer features that could predict treatment response." (PMID 36421674, 2022). "CD8+ cells infiltrating cancer-cell islets featured higher expression of proteins related to effector function (GZMB, CD127), T-cell co-stimulation and co-inhibition (PD-1, LAG3, 4-1BB, GITR, STING, B7-H3), and other non-T-cell co-inhibitory proteins (PD-L1, PD-L2), IDO1, and Ki-67." (PMID 38044986, 2023). "In contrast, high IDO1 expression levels in HCC patients have been correlated with better survival outcomes, indicating that IDO1 may not have immunosuppressive functions in this cancer." (PMID 34069452, 2021). "However, at odds with IDO1 inhibitors, TDO inhibitors are effective in synergistic immunotherapy with ICIs even though there is little or no TDO expression in cancers, which may be because the inhibitor of TDO could block hepatic TDO to increase systemic Trp levels." (PMID 35003126, 2021).
infection (216 papers, 2009 to 2026). The state of being infected such as from the introduction of a foreign agent such as serum, vaccine, antigenic substance or organism. "This adaptation allows it to withstand the local depletion of tryptophan caused by the host’s increased expression of IDO1 during infection." (PMID 39438693, 2024). "Prominent examples include VE/DE genes that encode IL1B and IDO1, suggesting that VE/DE genes are relevant to infection and disease progression." (PMID 37333188, 2023). "Here, we demonstrate that indoleamine 2,3-dioxygenase 1-deficient (IDO1-/-) mice display less severe AE as compared to wild-type (WT) mice during the infection." (PMID 36439161, 2022). "We also found strong promoter activity of another ISG candidate, IDO1, in infection, but significant loss of both p125-luc and IDO1 promoter activity was observed in β-catenin KO cells." (PMID 30770800, 2019). "Ablating IDO1 genes eliminated IDO activity in lungs and associated lymph nodes, and loss of IDO activity led to less morbidity during infection and faster recovery after viral clearance." (PMID 23785507, 2013). "The course of the infection was different in IL-22- vs. IDO1-deficient mice and in those mice vs. their respective wild-type counterparts." (PMID 23853597, 2013). "IDO-1 activity has also been implicated in modulating Th1 and Th17 responses during infection with Candida albicans and the balance between Th17 and regulatory T cell responses in HIV disease." (PMID 22649518, 2012). "The extent and quality of the inflammatory infiltrate in lungs of IDO-1 deficient mice were comparable to WT mice and equivalent survival post infection was observed in both WT and IDO-1−/− mice." (PMID 22649518, 2012). "We observed that IDO1 knockout strongly reversed the severe mortality caused by 17ZR101 infection." (PMID 40096073, 2025). "Additionally, we found a decrease in the Kyn:Trp ratio in the lungs of IDO1‐deficient mice after infection, suggesting that IDO1 is the major enzyme involved in kynurenine production in our model." (PMID 40387573, 2025). "However, we did observe a decreased frequency of IDO-1+ M-MDSCs at 72 h post infection in TLR4-deficient mice compared to WT controls." (PMID 37524886, 2023). "IDO-1 stimulation may however, lead to undesired effects, such as defective immunity and increased susceptibility to infection." (PMID 33117340, 2020). "The balance between the IDO1 and AhR pathways represents a surrogate for the status of the microbiota and the local immune system and a predictive factor for the susceptibility to infection and the disease course." (PMID 33322584, 2020). "Recently, IDO1 activity has been identified as a potential clinical marker of bacterial infection in hemodialysis patients, linking dysregulation of the immune system to hemodialysis chronic microinflammation and risk of infection." (PMID 31729973, 2019). "Such infection-associated induction of IDO1 was soon found to be mediated by IFN-γ." (PMID 24904580, 2014). "Similarly, in vivo administration of a pharmacological inhibitor of IDO to Toxoplasma gondii infected mice or infection of an IDO1-deficient mouse strain led to a more efficient control of parasite growth by IDO1-impaired hosts." (PMID 25505468, 2014). "Given that IDO-1 deficiency enhanced mycobacteria-specific T cell proliferation in vitro we examined the influence of IDO-1 on the generation of an antigen-specific T cell response following infection with M. tuberculosis in vivo." (PMID 22649518, 2012). "Our results suggest, that prolonged stressful experiences may aggravate the risk of suffer from infections in different disease states via IDO1 activation." (PMID 20689575, 2010). "Thus, the weak increase of IDO1 in IPP at the peak of infection that subsequently intensified at 11–12 dpi could be linked to the increase of IFNγ observed only during the resolution of infection." (PMID 38756777, 2024).